FOXO1 (forkhead box O1)
Diseases named in the same sentence as FOXO1 in open-access papers (continued):
Sharing a sentence is not in itself a finding about the gene and the disease.
Sepsis (continued). "Hence, FOXO1 is involved in the mechanism of sepsis through many different pathways." (PMID 31492105, 2019). "Importantly, treatment with GSK0660 reduced sepsis-induced loss of muscle mass and blunted (but did not completely prevent) sepsis-induced upregulation of FOXO1, atrogin-1 and MuRF1 mRNA and protein levels." (PMID 23555761, 2013). "Overall, these results demonstrate that FoxO1 enhances glycolysis in Tim4+ macrophages through MAP4K4 signaling, thereby driving pro-inflammatory responses in sepsis." (PMID 41362741, 2026). "FOXO1, KLHL3, and PCBP1 were weakly expressed in the sepsis group whereas MTF1, TMEM59, PIK3CB, and S100A9 were highly expressed in the sepsis group." (PMID 41542228, 2026). "Collectively, our results establish macrophage FoxO1 as a novel therapeutic target for septic intestinal injury and provide mechanistic evidence supporting the clinical potential of HSBD in treating sepsis-induced inflammation." (PMID 41362741, 2026). "We observed that sepsis decreased the levels of FOXM1 and its downstream targets, FOXO1, E2F3, and β-catenin but upregulated p21 in lung tissue." (PMID 41253746, 2025). "This study proves that miR-223 participate in the regulation of LPS-induced autophagy via the regulation of FOXO1 expression in CD4+ T lymphocytes which shed a new light for the diagnosis and treatment of sepsis." (PMID 39439897, 2024). "Microarray analysis has indicated abnormalities in the expression of immune-related genes in children with sepsis, including FYN, FBL, ATM, WDR75, FOXO1, and ITK." (PMID 36855207, 2023). "Dynamic changes in serum ACVR2A, FOXO1, IHH and STK4 levels in patients with sepsis during theirhospitalization in ICUs were evaluated." (PMID 24303815, 2014). "ROC analysis was then performed on ACVR2A, FOXO1, IHH and STK4 to evaluate the predictive valueof sepsis mortality." (PMID 24303815, 2014). "The opposite trend was observed for FOXO1; the SOFA and the APACHEII scores were at the highest levels in the mild sepsis group and at the lowest levels in the septicshock group." (PMID 24303815, 2014). "qPCR results showed that the expression of S100A9, PCBP1, PIK3CB, FOXO1, and TMEM59 was consistent with the public dataset, among which S100A9, PIK3CB, and TMEM59 were significantly overexpressed in sepsis, whereas PCBP1 and FOXO1 were significantly underexpressed in sepsis." (PMID 41542228, 2026). "We also demonstrated that FoxO1 directly bind to CEBPB in macrophages following LPS stimulation, revealing the complex molecular regulatory network in which FoxO1 acts as a pivotal transcription factor in sepsis." (PMID 41362741, 2026). "Thus, this study proved that miR-223 participate in the regulation of LPS-induced autophagy via the regulation of FOXO1 expression in CD4+ T lymphocytes which shed a new light for the diagnosis and treatment of sepsis." (PMID 39439897, 2024). "One of our previous studies showed that FOXO1 was a target gene of miR-223 and miR-15a/16, which are involved in the pathway of lymphocyte apoptosis during sepsis (data not shown)." (PMID 31492105, 2019). "In clinical studies and in in vivo models of sepsis, we have shown that elevation in circulating levels of HS precedes elevation in Angpt-2 levels; moreover, we observed that removal of HS from the eGC of HLMVEC promoted the upregulation in FoxO1 signaling to promote Angpt-2 upregulation." (PMID 39114570, 2024). "Although FoxO1 is not the sole molecular target of HSBD in sepsis, the marked inhibitory effect of HSBD on macrophage FoxO1 in septic mice suggests a promising therapeutic relationship that warrants further mechanistic investigation." (PMID 41362741, 2026).
Sepsis (continued). "Unlike prior studies in sepsis/metabolic disorders, we demonstrate miR-223’s IBD-specific regulation of PPAR-γ/FOXO1 crosstalk." (PMID 40799643, 2025). "However, to date, no study has shown whether FOXO1 SNPs are correlated with sepsis." (PMID 31492105, 2019). "Different roles of FoxO1 and FoxO3 in insulin and AMPK signaling have been suggested in previous in vitro non-muscle cell studies and in rat sepsis-induced muscle wasting." (PMID 21483870, 2011). "However, while various mechanisms involving the AKT/FOXO1/MAF1 regulatory axis have been studied in cancer, they have not been studied in sepsis." (PMID 39833662, 2025). "Indeed, recent findings showed that AMPK activation upon sepsis or AICAR injection increased FOXO3, FOXO1 but not FOXO4 mRNA levels in skeletal muscle of mice." (PMID 22848740, 2012).
colon carcinoma (38 papers, 2011 to 2025). "These authors also demonstrated that G9a protein expression is increased in human colon cancer patient tissue samples associated with a decrease in FOXO1 protein level." (PMID 34685453, 2021). "In the bladder, for example, FOXO1 is the target of miR‐1247‐3p,57 while miR‐135b‐5p (present in exosomes released by cancer‐associated fibroblasts) and miR‐183‐5p (in exosomes produced by tumor cells) repress FOXO1 in colon cancer." (PMID 40318053, 2025). "It is hypothesized that the increase in crypt foci and colon cancer risk through insulin activity may be related to the induction of G9a, resulting in methylation-mediated degradation of FOXO1." (PMID 36830954, 2023). "For instance, the degradation of the FoxO1 protein through G9a-catalyzed methylation can boost cell proliferation and worsen colon cancer." (PMID 40165083, 2025). "Loss of SIRT2 leads the endogenous FOXO1 acetylated in colon cancer by dissociating from SIRT2 and binding acetylated FOXO1 to the E1-like protein Atg7, which affects the autophagy process that leads to cell death and thus exerts an oncogenic effect." (PMID 39479446, 2024). "The transcription factor FOXO1 acts as a tumor suppressor, inhibiting the proliferation, migration, and invasion of various cancers, such as hepatocellular, lung, prostate, and colon cancer 17,28,29." (PMID 38617001, 2024). "To ascertain the impact of FOXO1 on WNT pathway gene expression in colon cancer, we treated HCT116 and SW480 cells with AS1842856." (PMID 37584250, 2023). "FOXO1 and ‐3 are required to maintain intestinal stem cells by preventing differentiation, suggesting a possible role in colon cancer." (PMID 36602390, 2023). "Tissue matrix analysis showed lower levels of FOXO1 expression in human colon cancer crypt cells compared to controls." (PMID 36830954, 2023). "A strong effect of FOXO1 on colon cancer cell proliferation was also observed, strongly suggesting the role of G9a-mediated FOXO1 methylation in CRC growth." (PMID 36830954, 2023). "This methylation enhances the interaction of FOXO1 with S-phase kinase-associated protein 2 (SKP2), an E3 ubiquitin ligase, resulting in the degradation of FOXO1 and increasing colon cancer cell proliferation." (PMID 35740522, 2022). "Consistently, an analysis based on fluorescence-activated cell sorting (FACS) indicates that, the apoptosis rates of human colon cancer cells are higher in the presence of FOXO1 than in FOXO1 knockdown cells." (PMID 35723050, 2022). "In colon cancer, G9a-induced proteasomal degradation of FOXO1-K273me1/2 proteoforms enhances colon cancer cell proliferation and colony formation." (PMID 33088284, 2020). "In addition, tumors originating from the rectum exhibit higher FOXO1 expression compared to colon tumors, suggesting region-specific differences in expression." (PMID 38891994, 2024). "To examine whether FOXO1 inhibition impacted colon cancer, we examined HCT116 and SW480 cell lines for colony formation upon AS1842856 treatment." (PMID 36602390, 2023). "Together, this data suggests that G9a-mediated degradation of FOXO1 may play an important role in colon cancer progression." (PMID 36830954, 2023). "Additionally, tissue samples of human colon cancer showed an inverse correlation between G9a and FOXO1 levels, with lower FOXO1 expression correlating with a poorer prognosis." (PMID 35740522, 2022). "FoxO1 degradation promotes cell proliferation in colon cancer." (PMID 34539243, 2021). "Moreover, cytosolic FoxO1 not only induces autophagic activity but also acts as a tumor suppressor in colon tumors." (PMID 34737955, 2021). "This event decreases FOXO1 protein stability and promotes cellular proliferation in colon cancer." (PMID 34685453, 2021). "Refining regulatory mechanisms that promote these WNT outputs, such as FOXO1‐mediated, will shed light on the biological underpinnings that drive GBM and colon cancer progression." (PMID 37584250, 2023).
colon carcinoma (continued). "FOXO1, FOXO3, and FOXO4 were significantly underexpressed in tumour samples: in breast, bladder and colon tumours for FOXO1, in breast tumours for FOXO3, and in breast, bladder, and colon tumours for FOXO4." (PMID 29484124, 2018). "In this network diagram, many genes were closely related with colon cancer progression such as PTEN, STAT3, FOXO1, and SMAD4." (PMID 28938919, 2017). "In contrast, other literature proposes that acetylated, rather than phosphorylated, FOXO1 plays a key role in autophagy regulation by interacting with ATG7 in the HCT116 colon cancer cell line." (PMID 41013182, 2025). "Mechanistically, NFIL3 has been found to block FOXO1 recruitment to certain tumor suppression-related genes and prevent the recruitment of Proline Acid Rich (PAR) transcription factors to pro-apoptotic genes in colon cancer." (PMID 38356719, 2024). "FOXO1 inhibition impacted AXIN2, LEF1, and TCF7 in some, but not all, examined BBC and colon cancer cell lines." (PMID 37584250, 2023).
sarcoma (38 papers, 2010 to 2026). A usually aggressive malignant neoplasm of the soft tissue or bone. "FOXO1 was most strongly associated with sarcoma (DOID:1115, with ELF1), and squamous cell carcinoma (DOID:5520, with ELF3) (k-mer = WAAACAGGAAG for both terms; mean k-mers Z-score > 5)." (PMID 31913281, 2020). "FOXO1 and FOXO3a mRNA levels were increased in three different sarcoma cell lines treated with ITF2357." (PMID 29472530, 2018). "To elucidate the role of FOXO1 in OS tumorigenesis, we first evaluated its expression levels in OS compared with other sarcomas." (PMID 26344693, 2015). "FOXO1 is a well-known TF that, in association with the coactivator PGC-1α (PPARGC1A), activates the gluconeogenic enzyme fructose 1,6-bisphosphatase (FBP), a putative inhibitor of sarcoma growth." (PMID 37834179, 2023). "As expected, lung tumors with driver fusions harbored mostly EML4/ALK fusions, sarcomas were driven mostly by EWSR1-related and PAX3/FOXO1 fusions, while hematologic malignancies with a spectrum of BCR/ABL1, KMT2A-related, and IGH/MYC fusions." (PMID 33889297, 2021). "PAX3/FOXO1 is the driver oncofusion in 70% of FP‐RMS and promotes phenotypes critical to both sarcoma growth and dissemination." (PMID 32697014, 2020). "It is thus clear that unravelling the transcriptional regulatory mechanisms of PAX3, FOXO1 and the oncogenic PAX3:FOXO1 gene should help to identify the elusive cell type of origin for these sarcomas." (PMID 28615069, 2017). "Altogether, cross-species comparison of transcriptome, methylome, and histology data revealed a coherent picture, indicating conservation of human sarcoma biology across the sarcoma EPO-GEMM cohort, especially for bona fide fusion-driven sarcomas SS18::SSX, NTRK-Mono, PAX3::FOXO1 and ASPSCR1::TFE3." (PMID 40523919, 2025). "Furthermore, they provide a strong rationale for the use of PROTACs in targeting gene fusions in paediatric sarcoma such as EWSR1::FLI1 and PAX3::FOXO1." (PMID 40983796, 2025). "In addition 100% concordance was achieved overall for the sarcoma panel containing SYT (SS18), EWSR1 and FOXO1 in the UK NEQAS International Quality Expertise 2017 evaluation." (PMID 31236139, 2019). "Also, increased expression of ASNS compared to normal human muscle was detected in 9 of 9 human sarcoma cell lines analyzed by PCR, including the PAX3:FOXO1-positive human RMS cell line Rh30." (PMID 26499495, 2015). "Pathologists might consider addressing this possibility in cases of pediatric and adolescent undifferentiated sarcomas and consider FISH for PAX3:FOXO1 in atypical cases." (PMID 25030697, 2014). "The manner in which Ets1 regulation by PAX3/FOXO1 and EWS/Fli1 tracks with the effects of the respective oncofusions on metastatic phenotypes suggests that Ets1 may have a more general, important role in sarcoma metastasis." (PMID 32697014, 2020). "Unlike kinase fusions present in other sarcomas involving NTRK3 or ALK, however, FOXO1 fusions lack an enzymatic, readily druggable activity." (PMID 36282590, 2022). "Notably, reduction of both FOXO1 and 3a did not inhibit the induction of Bim expression in response to ITF2357, and consequently did not protect sarcoma cells against ITF2357-induced apoptosis." (PMID 29472530, 2018). "Molecular classification has been proposed, dividing RMS into two basic groups: fusion-positive RMS (either PAX7::FOXO1 enriched or PAX3::FOXO1 enriched) and fusion negative RMS (which is further sub-divided into well differentiated RMS, moderately differentiated RMS, and undifferentiated sarcomas)." (PMID 39020398, 2024).
cervical carcinoma (37 papers, 2014 to 2025). A carcinoma arising from either the exocervical squamous epithelium or the endocervical glandular epithelium. "These three DE-ARGs have been reported to be associated with cancer, of which CHMP4C and FOXO1 have been shown to play an important role in the occurrence and development of cervical cancer." (PMID 33633773, 2020). "However, other studies evidence a controversy on the possible role of FOXO1 in cervical cancer, since its overexpression has been associated with a poor prognosis." (PMID 36497200, 2022). "GPX4 acts as a key anti-ferroptosis enzyme in cervical cancer, and its downregulation—triggered by MTCH1 deficiency and impaired FoxO1 nuclear translocation—leads to elevated ROS and ferroptotic cell death." (PMID 40895556, 2025). "The PTEN/AKT/FOXO1 pathway is also regulated by microRNA-181a to suppress the proliferation and invasion and promote the apoptosis of cervical cancer cells." (PMID 39833662, 2025). "This suggests the existence of a FOXO1/RIPOR2/RhoA axis mediated by HPV oncoproteins which is affected in cervical cancer and related to an unfavorable clinical outcome." (PMID 36497200, 2022). "Of interest, FOXO1 expression is decreased in CaSki and SiHa cells, but the regulation of FOXO1 in cervical cancer is not yet fully understood." (PMID 33121134, 2020). "In this study, FOXO1 expression was significantly lower in cervical cancer tissues than it was in normal tissues, and the FOXO1 gene was located upstream of the Rb gene in the PI3K/Akt signaling pathway." (PMID 32993576, 2020). "In contrast, the downregulation of FOXO1 promotes the invasion and metastasis of cervical cancer cells." (PMID 32993576, 2020). "FOXO1 expression inhibits cervical cancer development by bringing about cell cycle arrest and apoptosis and is a favorable prognostic factor." (PMID 31366565, 2019). "Another study has reported that inhibition of miR-181a promotes apoptosis of cervical cancer cells through PTEN/Akt/FOXO1." (PMID 31467256, 2019). "It has been suggested that the AKT/FOXO1 signaling pathway plays an important role in several cancers especially in breast, thyroid and cervical cancers." (PMID 30769922, 2019). "Some studies also indicated that SC66 effectively inhibited the phosphorylation levels of AKT through disruption of mTOR signaling, and therefore contributes to decrease the expressions of p-GSK-3β and p-FOXO1 in human cervical cancer." (PMID 31168297, 2019). "Studies in cervical cancer suggest it has a role in regulating cell proliferation and that it targets p27, FOXO1 and the (PI3K) AKT pathway, and HOXC8, a cell remodeling protein." (PMID 26544609, 2015). "Interestingly, our findings aligned with a prior study about another isoform of FOXO that noted reduced FOXO1 mRNA expression in both primary tumor biopsies and cell lines of cervical cancer." (PMID 39655333, 2024). "On a mechanistic level, GAS5 may increase radiosensitivity in cervical cancer cells via miR-106b and upregulation of forkhead box O1 (FOXO1) and PTEN by sponging miR-196a and miR-205." (PMID 34830902, 2021). "Overexpression of FOXO1 in vitro can inhibit the growth and proliferation of cervical cancer cells." (PMID 32993576, 2020). "The role of FOXO1 in the development of cervical cancer is still controversial." (PMID 32993576, 2020). "Concerning the mechanism of CIN occurrence, FOXO1 might have a tendency to be overexpressed to inhibit the progression of lesions to cervical cancer." (PMID 32993576, 2020). "This suggests that FOXO1 has a dual role in cervical cancer and needs to be further researched." (PMID 33633773, 2020). "Additionally, FOXO1 localization in cervical cancer cells revealed a similar outcome." (PMID 37880374, 2023). "Thus, the low expression of FOXO1 may be linked to the excessive proliferation of cells, which may promote the progression of CIN to cervical cancer." (PMID 32993576, 2020).
cervical carcinoma (continued). "However, some studies reported that inhibiting FOXO1 expression could inhibit cervical cancer growth." (PMID 32993576, 2020). "Moreover, the prognosis of cervical cancer with FOXO1 overexpression is more satisfactory." (PMID 32993576, 2020). "Interestingly, FOXO1 has also been found to act as a tumor suppressor in cervical cancer cells." (PMID 33633773, 2020). "We also found that FOXO1 inhibition suppressed DTL-induced EMT and reduced the invasion and migration of cervical cancer cells." (PMID 34635635, 2021). "In U2OS cells, TSA promoted autophagy by inhibiting the mTOR (mammalian target of rapamycin) signaling pathway and enhancing forkhead box O1 (FOXO1) transcriptional activity, while it induced autophagy through regulating the PRMT5/STC1/TRPV6/JNK pathway in cervical cancer cells." (PMID 40283998, 2025). "In addition, our current study showed the down-regulated expression of FOXO1 and the up-regulated expression of C-myc in GDF15-overexpressing cervical cancer cells." (PMID 29636108, 2018). "Hou and colleagues showed that miR-196a directly targeted FOXO1 and p27Kip1, two key effectors of PI3K/Akt signaling; when overexpressed, miR-196a increased proliferation and G1/S-phase transition of cervical cancer cells whereas its suppression had the opposite effect." (PMID 29682211, 2018). "Cervical cancer cells gain the mesenchymal phenotype and lose the epithelial characteristic features during tumor progression, and UBE2T promoted the ubiquitination-mediated FOXO1 degradation to facilitate the epithelial-mesenchymal transition of non-small cell lung cancer." (PMID 34703898, 2021).